RNU6-601P (RNA, U6 small nuclear 601, pseudogene)
Gene: Small nuclear RNA gene on chromosome 2 (149,610,668 to 149,610,774, reverse strand). Ensembl gene ENSG00000207270.
Homologues: Orthologues: chimpanzee U6 (97% identical), macaque U6 (91% identical), pig U6 (75% identical). Paralogues in human: RNU6-16P (84% identical), RNU6-73P (84% identical), RNU6-49P (83% identical), RNU6-820P (83% identical), RNU6-1029P (82% identical), RNU6-1179P (82% identical), RNU6-12P (82% identical), RNU6-13P (82% identical), RNU6-25P (82% identical), RNU6-29P (82% identical), RNU6-32P (82% identical), RNU6-38P (82% identical), and 1287 more.